CRP (C-reactive protein)
Diseases named in the same sentence as CRP in open-access papers (continued):
Sharing a sentence is not in itself a finding about the gene and the disease.
delirium (continued). "The inflammatory biomarkers (SII, NLR, PLR, and CRP) were consistently elevated in the POD group, reinforcing inflammation’s role in delirium pathogenesis." (PMID 40572710, 2025). "A recent meta-analysis confirmed a statistically significant link between CRP, IL 6, and TNF-α with the development of delirium." (PMID 41010627, 2025). "The upregulation of acute inflammatory markers in our study, notably IL-6, CRP, and SAA following CPB exposure, is consistent with the neuroinflammation model of delirium." (PMID 40648974, 2025). "We have summarized the 13 most studied proteins (IL-6, CRP, IL-8, S100B, IL-10, TNF-a, IL-1b, Cortisol, MCP-1, GFAP, IGF-1, IL-1ra and NFL) about delirium." (PMID 39700095, 2024). "However, the relationship between CRP and delirium mortality remains unclear." (PMID 38523173, 2024). "The pooled analysis of the included studies revealed that patients with higher preoperative CRP (SMD 0.43, 95% CI 0.19–0.67) or lower preoperative ALB levels (SMD ‐0.35, 95% CI ‐0.59 to ‐0.12) were more prone to develop delirium following TJA." (PMID 39259060, 2024). "Pre-operative C-reactive protein (CRP) is significantly higher (7.0 ± 15.2 mg/L, p < 0.017) in patients with delirium, and values above 7 mg/L are especially considered predictive of POD." (PMID 36826366, 2023). "Our results showed that markers of impaired kidney function (urea, creatinine), liver injury (ALT, INR), and inflammation (CRP, PCT) significantly differed between the delirium and non-delirium groups." (PMID 37568451, 2023). "Overall, pooled analysis showed a significant increase in some serum biomarkers (i.e., CRP, TNF-α, and IL-6) of patients who developed delirium (OR = 1.88, 95% CI 1.01 to 1.637; I2 = 76.75%)." (PMID 37251808, 2023). "This study aimed to investigate the relationship between serum C-reactive protein (CRP)/Albumin ratio (CAR) and postoperative delirium (POD) in patients older than 60 years following total knee arthroplasty (TKA)." (PMID 36051706, 2022). "The effect of CRP, Alb, CAR on predicting delirium was assessed with the area under the receiver operating characteristic (ROC) curve (AUC)." (PMID 36051706, 2022). "The relationship between higher cytokines levels (IL-6), C-reactive protein (CRP) and delirium was previously observed in the population of ICU patients and individuals after non-cardiac surgery." (PMID 35175161, 2022). "At the same time, several clinical studies have investigated the relationship between CRP and POD in elderly patients, and they found that CRP levels were highly correlated with the onset of delirium." (PMID 36051706, 2022). "Patients' serum CRP, delirious status (using the confusion assessment method (CAM)), and delirious score (using the memorial delirium assessment scale (MDAS)) were examined before surgery and 1-2 days after surgery." (PMID 32851079, 2020). "Our analysis showed a similar correlation between NLR and CRP in patients with AIS and delirium on admission to hospital." (PMID 31336587, 2019). "The patients in the delirium group had a lower functional level before hospitalisation (NEADL), as well as higher inflammatory markers (CRP and leukocytes) than the control group." (PMID 30683068, 2019). "We found that prognostic information was contained in 9 predictors: age, low physical activity, hearing impairment, heavy alcoholism, history of prior delirium, ICU admission, emergency surgery, open surgery, and increased preoperative CRP." (PMID 27015177, 2016). "Delirium patients were matched with non-delirium patients after cardiac surgery on age, gender, severity of illness score, LOS-ICU, Euro-score, C-reactive protein, renal function and aorta clamping time." (PMID 21426560, 2011). "Serum creatinine, CRP, and NT-pro BNP levels were significantly higher in the delirium group." (PMID 40573090, 2025).
delirium (continued). "Inflammatory markers such as IL-6, IL-2, TNF-α, and C-reactive protein have been found to be elevated in POD patients compared to those without delirium." (PMID 40092071, 2025). "Adding delirium modestly increased the index’s discrimination (AUC, 0.723; 95% CI, 0.702-0.749); additionally including frailty and C-reactive protein level did not improve discrimination further (AUC, 0.723; 95% CI, 0.701-0.744)." (PMID 39841475, 2025). "We previously used mass-spectrometry-based plasma proteomics to define a preoperative delirium multi-protein signature that includes zinc-alpha-2-glycoprotein (AZGP1) and c-reactive protein (CRP) and a postoperative signature of interleukin-6 (IL-6), interleukin-2 (IL-2), and CRP." (PMID 39199312, 2024). "Among others, elevated CRP and WBC levels have been found in patients with delirium symptoms." (PMID 36928887, 2023). "Only 6 studies were eligible for the meta-analysis, pooled results showed a significant increase in some serum biomarkers (C-reactive protein [CRP], tumour necrosis factor alpha [TNF-α] and interleukin-6 [IL-6]) among patients with delirium (odds ratio = 1.88, 95% CI 1.01 to 1.637; I2 = 76.75%)." (PMID 37251808, 2023). "The data demonstrated an interaction of preoperative plasma homocysteine and postoperative plasma CRP on the incidence, but not severity, of postoperative delirium in patients." (PMID 36212043, 2022). "Several authors have detected higher CRP levels in older or very older people presenting delirium than in non-delirious patients." (PMID 36013306, 2022). "The average age and the ferritin and CRP levels were significantly higher among patients with delirium than among those without delirium, whereas the lymphocyte percentage was found to be significantly lower in those with delirium." (PMID 35476075, 2022). "Mean age, ferritin levels and CRP values ​​of those with delirium were higher, while the mean lymphocyte percentage were lower, than those of the patients without delirium." (PMID 35476075, 2022). "Nevertheless, moderately elevated inflammatory markers, especially C-reactive protein (CRP), might suggest a dysregulated immune response as a possible delirium precipitant." (PMID 35463530, 2022). "In further analyses, the CRP level of the non-hypoactive group was more increased than that of the hypoactive group during the delirium onset." (PMID 34912245, 2021). "In detail, the CRP level in the non-hypoactive group was significantly increased than that in the hypoactive group during delirium onset." (PMID 34912245, 2021). "Increased NLR levels were the unique response only in the delirium group whereas CRP levels were elevated over time both in delirium and non-delirium groups." (PMID 34912245, 2021). "There was a significant difference in age, ASA classification, surgery types, mean MDAS score, and postoperative CRP value between those patients having and not having postoperative delirium." (PMID 32851079, 2020). "Circulating plasma proteins, including pro-inflammatory makers like C-reactive protein and IL-6, have been recently correlated with patients developing delirium after non-cardiac surgery." (PMID 31911786, 2019). "The pre-operative value of the CRP differed significantly between patients with and without delirium (p = 0.015), with levels 6.33 ± 12.34 vs. 4.06 ± 7.80, respectively." (PMID 31684066, 2019). "CRP levels were also higher in patients experiencing delirium compared with those who did not (14.5 mg/dl vs 10.8 mg/dl, p<0.001)." (PMID 29570715, 2018). "Biochemical markers (CRP, platelets, haemoglobin and urea), all contributed information to prediction models but were bidirectional in their importance, suggesting complex non-linear relationships with delirium incidence." (PMID 41462244, 2025).
delirium (continued). "The inflammatory biomarkers C-reactive protein and procalcitonin (p = 0.005 and 0.006) as well as serum creatinine (p = 0.014) and urea (p = 0.021) were significantly elevated in delirious patients when compared to those without delirium." (PMID 37854697, 2023). "Mean CRP serum concentrations at hospital admission were reported in 15 studies, with a difference of 41.39 mg/L between the means that is greater in patients who developed delirium than in those who did not." (PMID 37360340, 2023). "In summary, the MR analysis indicated that there may not be a causal association between delirium and the following factors: TNF-α, CRP, IL-1α, IL-1β, IL-2, IL-6, sIL-6Rα, soluble gp130, and IL-8." (PMID 37649721, 2023). "In addition, ferritin (p=0.04) and CRP levels (p=0.015) were found to be significantly higher and lymphocyte levels (p=0.048) were significantly lower in patients with delirium than in those without delirium." (PMID 35476075, 2022). "However, serum CRP and creatinine values in the delirium group were higher than those in the no delirium group, and the estimated glomerular filtration rate was significantly lower in the delirium group." (PMID 35962209, 2022). "For example, one study showed increased IL-6, IL-2, and IL-1α levels in delirium due to septic shock, although no such increases in CRP, CXCL8 and TNF-α could be established." (PMID 35641947, 2022). "The probability of delirium was not affected by C-reactive protein (CRP) (p = 1.000)." (PMID 36413529, 2022). "Third, other inflammatory markers (e.g., CRP, IL-6, or IL-8), which may have influence on delirium, were not included in our study." (PMID 34034650, 2021). "Since both NLR and CRP levels may serve as potential predictors and biomarkers for delirium, the present study examined the role of NLR and CRP, especially in patients with delirium in the ICU." (PMID 34912245, 2021). "The results of this study are consistent with those previous studies, but the previous studies were all reports on elderly (over 70 years old) nonsurgical patients or critical patients, and their basic CRP level and delirium incidence are significantly higher than this study." (PMID 32851079, 2020). "CRP levels were also higher in patients experiencing delirium compared with those who did not." (PMID 29570715, 2018). "Significant differences between the delirium and non-delirium groups were observed in terms of age, TBI classification, sleep duration, CRP levels, TNFα levels, pain scores, self-efficacy, and insomnias (P < 0.05)." (PMID 39554848, 2024). "Patients with delirium differed significantly from those without delirium in age, TBI classification, sleep duration, CRP levels, TNF-α levels, pain, self-efficacy, and insomnia (P < 0.05)." (PMID 39554848, 2024). "Although current evidence does not favour the use of any particular biomarker, serum CRP, TNF-α, and IL-6 were the most consistent biomarkers of delirium in older patients." (PMID 37251808, 2023). "The CRP levels and WBC counts have been compared but were only measured once, which is still remained unclear between patients with and without delirium." (PMID 34912245, 2021). "Serum levels of CRP and ESR between patients with and without postoperative delirium were similar (P=0.354 and P=0.589)." (PMID 24093540, 2013). "In this study, the preoperative clinical data, blood routine and biochemical indexes of 268 patients over 60 years old undergoing TKA were compared, and it was found that there were statistical differences in CRP, Alb, CAR between the delirium group and the without delirium." (PMID 36051706, 2022). "The lack of reduced POD incidence despite lower systemic inflammation in the R-TIVA group suggests that the systemic biomarkers (e.g., NLR and CRP) may not fully reflect neuroinflammation, which is likely a key driver of POD pathogenesis, highlighting the multifactorial nature of delirium." (PMID 40572710, 2025).
thrombosis (168 papers, 2007 to 2025). "Inflammatory markers, such as CRP, have been associated with both arterial and venous thrombosis in obese individuals." (PMID 40002762, 2025). "This is supported by findings that inflammatory markers, such as CRP, are associated with arterial and venous thrombosis in obese individuals." (PMID 40002762, 2025). "Both C reactive protein and mean platelet volume have also been associated with increased risk of thrombosis, or blood clots that obstruct normal blood flow." (PMID 39825393, 2025). "Here, we developed nanoengineered multichannel immunosensors for rapid detection of circulating biomarkers associated with thrombosis, including C-reactive protein (CRP), calprotectin, soluble platelet selectin (sP-selectin), and D-dimer." (PMID 39661669, 2024). "CRP has previously been associated with thrombosis formation and an increased risk of thromboembolism in other settings, but is a non-specific marker that increases with several complications." (PMID 37063904, 2023). "In particular, IL-6 seems to play a critical role in inflammation-related thrombosis, together with tumor necrosis factor-alpha (TNFα), interleukin 8 (IL-8), and C-reactive protein (CRP), representing powerful risk predictors for DVT." (PMID 35625609, 2022). "While both test results were associated with increased hospital mortality, the adjusted association was stronger for CRP (a biomarker of inflammation) than for D-dimer levels (a biomarker of thrombosis), even when adjusted for each other." (PMID 34909913, 2021). "After adjusting for CRP, LA was found to be independently associated with thrombosis (odds ratio, 4.39; 95% CI, 1.45-14.57; P = .01)." (PMID 32785632, 2020). "As previously reported, the potential correlation between hs-CRP values and the risk of thrombosis and cardiovascular disease led us to evaluate the incidence of VTE in our patients." (PMID 26848624, 2016). "Although our data failed to confirm that hs-CRP is predictive of the risk of thromboembolic events, it is noteworthy that hs-CRP values in patients who developed thrombosis tended to increase during the course of treatment." (PMID 26848624, 2016). "Among the four biomarkers evaluated, CRP exhibited the most significant statistical association with thrombosis, as evidenced by the lowest P value (P = 0.0191) and the highest area under the curve (AUC = 0.773) in ROC analysis, outperforming calprotectin, sP-selectin, and D-dimer." (PMID 39661669, 2024). "In addition, elevated CRP levels are associated with thrombosis and vascular endothelial dysfunction." (PMID 38893671, 2024). "The association between CRP and PE may be the result of upregulation of inflammatory mediators during acute thrombosis." (PMID 36952456, 2023). "Overall, this evidence suggests that individuals with cancer and a higher circulating CRP level have an increased risk of developing a first thrombosis, and a higher risk of recurrence following treatment for CAT if the CRP level remains high after cessation of anticoagulation." (PMID 36177015, 2022). "Abdominal thrombosis may also account for these symptoms and interestingly, has been previously associated with elevated levels of CRP, an inflammatory marker elevated in both MPN and smokers." (PMID 34112113, 2021). "Our findings might shed light on the mechanism of higher leukocyte count increased the risk of bleeding and higher hs-CRP increased the risk of thrombosis." (PMID 34671655, 2021). "Indeed, C-reactive protein was independently associated with the presence of a deep-vein thrombosis demonstrated by duplex ultrasound as well as a pulmonary embolism demonstrated by computed tomography pulmonary angiography." (PMID 34441957, 2021). "These might increase the risk of venous thrombosis and could include changes in levels of hemostatic factors and C-reactive protein (CRP)." (PMID 28540474, 2017).
thrombosis (continued). "Therefore, the aim of our study was to assess the association between lipid levels and risk of venous thrombosis, and to evaluate the underlying mechanism, with particular attention to confounding and mediation via hemostatic factors and CRP." (PMID 28540474, 2017). "Therefore, this study was performed to investigate correlation of vitamin D level with plasma P-selectin, hs-CRP and risk factors of thrombosis in these subjects." (PMID 24734087, 2014). "In conclusion, platelet count, CRP, and the vertical distance from the highest point of the catheter to the upper border of the left and right extremitas sternalis claviculae might be the risk factors for TIAPs-associated thrombosis." (PMID 36864082, 2023). "Platelet count, C-reactive protein, and the vertical distance from the highest point of the catheter to the upper border of the left and right extremitas sternalis claviculae were demonstrated to be the main risk factors for the development of TIAPs-associated thrombosis." (PMID 36864082, 2023). "Hemoglobin (P = 0.073), platelet count (P = 0.001), CRP (P = 0.002), and the vertical distance from the highest point of the catheter to the upper border of the left and right extremitas sternalis claviculae (P = 0.05) were identified as risk factors for developing TIAPs-associated thrombosis." (PMID 36864082, 2023). "High-sensitivity C-reactive protein levels may also be used to predict the risk of venous thromboembolism recurrence after discontinuation of anticoagulant treatment, in patients with cancer-associated thrombosis." (PMID 32168924, 2020). "All other extraordinary findings within this syndrome such as gastric retention, arterial and venous thrombosis, loss of smell, disproportional weight loss, relatively high CRP, hemodynamic stability and the limited need for insulin might be explained by hyperleptinemia." (PMID 32844126, 2020). "We aimed to assess the association between several lipids and risk of venous thrombosis using data from a population-based case–control study, and to evaluate the underlying mechanism, considering confounding by common risk factors and mediation via hemostatic factors and C-reactive protein." (PMID 28540474, 2017). "The concomitant elevation of both hemostatic (FVIII, vWF) and inflammatory (fibrinogen, CRP) markers observed in patients with a SYNTAX score ≥33 suggests a complex interplay between thrombosis and inflammation in atherosclerotic disease." (PMID 41007843, 2025). "C-reactive protein (CRP) is well-known to be elevated in deep vein thrombosis (DVT) and PTE; however, recent studies remain inconclusive regarding its direct inflammatory role, and some have found no predictive value of CRP for PTE severity." (PMID 41155817, 2025). "Elevated CRP levels have been linked to an increased risk of venous thromboembolism (VTE), particularly deep vein thrombosis (DVT), in cancer patients." (PMID 40565133, 2025). "Initial workup revealed markedly elevated C-reactive protein and D-dimer levels with extensive bilateral deep vein thrombosis (DVT)." (PMID 40951190, 2025). "Certain coagulation index such as D-dimer and fibrinogen, as well as inflammatory index including platelet-to-lymphocyte ratio and serum C-reactive protein, have been validated as predictors of deep vein thrombosis post-ICH." (PMID 40070667, 2025). "Regarding AMI involving the thrombosis or embolism of the mesenteric artery, the neutrophil–lymphocyte ratio and CRP can be used, with values over 12.5 × 103/μL and 19.4 mg/L, respectively, indicating a positive diagnosis." (PMID 38611583, 2024). "By multivariate logistic regression analysis, CRP, CVL insertion, and duration of NICU admission were independently associated with a higher risk of thrombosis with adjusted ORs of 1.02, 7.7, and 1.11, respectively (p < 0.001)." (PMID 39349608, 2024).